GSK3B (glycogen synthase kinase 3 beta)
Diseases named in the same sentence as GSK3B in open-access papers (continued):
Sharing a sentence is not in itself a finding about the gene and the disease.
osteosarcoma (continued). "Functionality of EGFR in osteosarcoma cells was proven by EGF-mediated activation of both MAPK and PI3K/AKT pathway (determined by phosphorylation of ERK1/2, AKT, S6, and GSK3β)." (PMID 26526352, 2015). "In the canonical Wnt signaling pathway, the following genes were significantly deleted across the osteosarcoma dataset: WNT, FRP, Frizzled, GBP, GSK-3β, TCF/LET, TAK1, CK1, CtBP, and B-TrCP." (PMID 24942472, 2014). "Additionally, PHLDA2 has been shown to impact EMT and metastasis in osteosarcoma through the SRC/PI3K/AKT/mTOR and WNT/GSK3-β/β-catenin signaling pathway." (PMID 38827322, 2024). "Additionally, GSK3B-KO NK cells showed similar killing potency as WT NK cell against HL60 (AML), K562 (CML), DAOY (medulloblastoma), and MG63 (osteosarcoma) in a standard 4 h killing assay." (PMID 36765663, 2023). "Furthermore, PIP also attenuated the initiation of the PI3K/AKT/GSK-3β signaling pathway in osteosarcoma cells by altering the expression levels of P-AKT, P-PI3K and P-GSK3β." (PMID 36895009, 2023). "The expressions of GSK3β in tissue samples of 24 patients with primary metastatic osteosarcoma and 16 patients with nonmetastatic osteosarcoma were detected by the immunohistochemical staining." (PMID 33969873, 2021). "In order to explore the activity of phosphorylating β-catenin, substrates of GSK3β, in human osteosarcoma cells and nontumor cells, we performed the NRIKA analysis in these cells." (PMID 33969873, 2021). "To test whether GSK3β inhibition and knockdown cells were defective in HRR, we chose a well-characterized reporter assay using the DR-U2OS, a human osteosarcoma cell line with chromosomally integrated HR reporter gene containing an I-SceI recognition sequence." (PMID 33589588, 2021). "In osteosarcoma, miR-135b promotes cell proliferation and invasion by targeting FOXO142 and stimulates recurrence and lung metastasis by targeting TET3 and multiple negative regulators of the Wnt/β-Catenin, including APC, CK1α, GSK3β, and β-TrCP43." (PMID 33990540, 2021). "Inhibition of GSK-3 activity with lithium chloride, SB216763, inhibitor IX (BIO) or with siRNA specific for GSK-3β resulted in suppression of GSK-3β and NF-κB activities and cellular proliferation and induction of apoptosis in human osteosarcoma cells in vitro and in mouse xenograft studies." (PMID 32365809, 2020). "Notably, in osteosarcoma (OS), p-AKT expression decreased after knockout of hsa_circ_0007534, and the expression trend of p-GSK-3β was consistent with p-AKT." (PMID 33052244, 2020). "Reduction of the level of GSK-3β expression by RNA interference affected osteosarcoma, but not osteoblast proliferation, apoptosis and survival." (PMID 27780915, 2016). "A study on osteosarcoma demonstrated that zeylenone could synergize with cisplatin, enhancing cisplatin efficacy by inducing DNA damage and cell cycle arrest and activating the AKT/GSK3β signaling pathway." (PMID 38264522, 2023). "The immunohistochemistry staining results showed that the percentage of GSK3β positive cells in the tumor samples of patients with primary metastatic osteosarcoma was markedly higher than that of patients without metastasis (67.8 ± 5.8% vs. 24.8 ± 3.6%, P<0.001)." (PMID 33969873, 2021). "However, the roles of GSK-3β in the process of invasion and metastasis of osteosarcoma are still not clear." (PMID 33969873, 2021). "Compared with normal human osteoblast cells (hFOB1.19), the human osteosarcoma cells (MG63, SaOS-2, and U2-OS) showed higher protein expression levels of GSK3β and active form of GSK3β (p-GSK3βTyr216), while lower levels of inactive form of GSK3β (p-GSK3βSer9)." (PMID 33969873, 2021). "Whether or not URG4 is involved in the biological behavior of osteosarcoma cells through the GSK-3β/β-catenin pathway is still unknown." (PMID 32552851, 2020).
osteosarcoma (continued). "There are currently no WNT modulators in specifically osteosarcoma trials, but there are a few trials targeting WNT in solid tumors (FOG-001, E7386, SM08502, and ST316 (β-catenin inhibitors), CGX1321, RXC004 and ETC-1922159 (porcupine inhibitors), and 9-ING-41 (a GSK-3β inhibitor))." (PMID 39102216, 2024).
bladder cancer (61 papers, 2010 to 2025). "Nuclear accumulation of GSK3B is associated with progression and poor survival of bladder cancer patients; GSK3B knockdown inhibits the viability of bladder cancers." (PMID 41287122, 2025). "nuclear expression of GSK-3β was associated with high malignancy, metastasis and poorer survival in bladder cancer patients." (PMID 36316768, 2022). "Moreover, GSK3β has been associated with worse clinical outcomes in bladder cancer." (PMID 31001473, 2019). "DEA showed similar effects in reducing p-AKT in cell lines from different types of cancers, including the bladder cancer cell line T24, in which GSK-3β was also reduced." (PMID 40353763, 2025). "Recent studies have found that stevia glycosides can induce apoptosis by activating GSK‐3β and endoplasmic reticulum (ER) stress signaling pathways, thereby inhibiting bladder cancer development." (PMID 39898123, 2025). "Lidocaine, as a robust autophagy inducer, inhibits the growth of bladder cancer cells through GSK3β signaling." (PMID 38610945, 2024). "Knockdown of TRIM26 led to the inhibition of proliferation, migration, and invasion of bladder cancer cells by impeding the AKT/GSK3b/b-catenin pathway." (PMID 38260302, 2024). "Increased FBXW7 activated GSK-3β phosphorylation and inhibited the expression of SREBP1a in bladder cancer cells." (PMID 37215134, 2023). "One study has demonstrated that GSK3β is involved in the β-catenin/Snail1 pathway to promote the EMT process in bladder cancer." (PMID 37608369, 2023). "Apart from being involved in autophagy, TP53INP2 can modulate epithelial-to-mesenchymal transition via the GSK-3β/β-Catenin/Snail1 pathway in bladder cancer cells." (PMID 36675134, 2023). "In another report, TRIM26 exerted an oncogenic role in bladder cancer and depletion of TRIM26 in bladder cancer cells slowed down tumor progress by inhibiting Akt/GSK3β/β-catenin pathway." (PMID 37591850, 2023). "C-Met is involved in miR-433-mediated inhibition of the EMT process in bladder cancer through modulating the Akt/GSK-3β/Snail signaling pathway." (PMID 35044621, 2022). "In contrast, miR-135a was found to accelerate the EMT and invasion in bladder cancer by targeting GSK3β and activating the Wnt/β-catenin pathway." (PMID 32944391, 2020). "It was shown that miR-137 targets SP1 and glycogen synthase kinase 3 beta (GSK3β) in bladder cancer and urothelial cancer, respectively." (PMID 33066509, 2020). "Glycogen synthase kinase-3 beta (GSK-3β), a serine/threonine kinase, has been identified as a potential therapeutic target in human bladder cancer." (PMID 31882719, 2019). "Pharmacologic inhibition or genetic depletion of GSK-3β resulted in a decreased viability of bladder cancer cells." (PMID 31882719, 2019). "Conversely, several studies demonstrated that GSK3β was accumulated in the nucleus in pancreatic, renal and bladder cancers." (PMID 24618715, 2014). "Furthermore, KIFC1 has been shown to enhance bladder cancer cell proliferation and induce epithelial-mesenchymal transformation via the Akt/GSK3β signaling pathway." (PMID 40379626, 2025). "In selecting 9‐ING‐41 (Elraglusib) for our study, we considered its unique profile as a reversible ATP‐competitive GSK‐3 inhibitor that has shown significant inhibition of GSK‐3β activity and preclinical antitumor activity in several cancers, including pancreatic and bladder cancers." (PMID 40905109, 2025). "Similarly, OSU-T315, an inhibitor of integrin-linked kinase, was observed to inhibit Mcl-1 expression levels via targeting the GSK-3β/FBXW7 axis in bladder cancer cells." (PMID 37215134, 2023). "Moreover, targeting GSK3β with 9-ING-41 (a small molecule inhibitor of GSK3β) has been observed to have multiple anti-bladder cancer effects, including cell cycle arrest, autophagy, and apoptosis in bladder cancer cells." (PMID 37608369, 2023). "TRIM26 exerts an oncogenic effect in bladder cancer via AKT/GSK3β/β-catenin." (PMID 36261847, 2022).
bladder cancer (continued). "In addition, it accelerates the migration and invasion of bladder cancer cells by downregulating glycogen synthase kinase 3 beta (GSK3β) to activate the Wnt/β-catenin pathway." (PMID 32944391, 2020). "Therefore, to elucidate the molecular mechanisms of DLX6-AS1 in regulating bladder cancer progression, we focused on the Wnt/β-catenin signaling pathway, and determined the expression of several key factors including β-catenin, GSK-3β c-myc and cyclin D1." (PMID 31787849, 2019). "In bladder cancer, GSK-3β positively regulates cell proliferation and survival in vitro." (PMID 26388612, 2015). "We therefore determined whether APF-induced decreased Akt phosphorylation lead to changes in GSK3β and β-catenin phosphorylation in T24 bladder carcinoma cells." (PMID 21143984, 2010). "Notably, this study found that the expression levels of AKT1, GSK3B, CASP3, TNF, and CCND1 were associated with immune cell infiltration in bladder cancer, suggesting that these targets could be used as potential predictors of bladder cancer immunotherapy." (PMID 41287122, 2025). "High expression of KLFC1 promoted the phosphorylation of glycogen synthase kinase 3 beta (GSK3β) and enhanced the expression of SNAI1 (encoding snail family transcriptional repressor 1) via protein kinase B (AKT) activation, which induced bladder cancer cell growth and EMT." (PMID 35811688, 2022). "RAC-alpha serine/threonine-protein kinase 1 (AKT1), glycogen synthase kinase 3 beta (GSK3B), caspase-3 (CASP3), tumor necrosis factor (TNF) and cyclin D1 (CCND1) were identified as the main hub targets of COP in bladder cancer treatment." (PMID 41287122, 2025). "In bladder cancer, TP53INP2 influences cell migration, invasion, and epithelial-mesenchymal transition (EMT) by regulating the GSK-3β/β-catenin/Snail1 pathway." (PMID 40755754, 2025). "The results showed that compared with normal tissues, ESR1, PTGS2 and BCL2 in bladder cancer tissues were significantly down-regulated; CASP3, INS, SRC, CDK4, GSK3B and ERBB2 were significantly up-regulated." (PMID 41287122, 2025). "Studies have reported that microRNA-135a can activate the Wnt/β-catenin signaling pathway by downregulating glycogen synthase kinase 3β (GSK-3β), thereby accelerating the EMT and migration of bladder cancer cells." (PMID 41387479, 2025). "Knockdown of TRPM8 in bladder cancer cells decreases p-AKT and increases p-GSK-3β level, which alters the process regulated by the AKT/GSK-3β signaling." (PMID 37033630, 2023). "Stevioside was identified by high-throughput screening as a useful compound to increase cell apoptosis via activation of GSK-3β and induction of FBXW7, contributing to downregulation of MCL-1 in bladder cancer." (PMID 37215134, 2023). "TRIM26 exerts an oncogenic role in bladder cancer through the regulation of cell proliferation, migration, and invasion via the AKT/GSK3β/β-catenin pathway." (PMID 36261847, 2022). "Over-expressed miRNA-940 promoted proliferation, migration, and invasion of bladder cancer cell and inhibited cell apoptosis by mediating INPP4A or GSK3β and activating the Wnt/β-catenin pathway." (PMID 34338136, 2021). "MAEL has different molecular mechanisms in different tumor types in which it activates the AKT/GSK-3b/SNAIL signaling in HCC, inhibits the E-cadherin in CRC, inhibits the MTSS1 in bladder cancer, and inhibits ILKAP tumor suppressor in GC." (PMID 33902648, 2021). "In the present study, we tested the GSK-3β inhibitor 9-ING-41, a targeted therapeutic currently being evaluated in a phase 1/2 clinical trial in advanced cancer patients, in bladder cancer cell lines." (PMID 31882719, 2019). "In the present study, we investigated the antitumor effect of a small molecule GSK-3β inhibitor, 9-ING-41, currently in clinical studies in patients with advanced cancer, in bladder cancer cell lines." (PMID 31882719, 2019).
bladder cancer (continued). "In bladder cancer cells LY294002, a PI3K inhibitor, inhibits phosphorylation of AKT and GSK3β, and ZEB1 expression due to inhibition of β-catenin/transcription factor 4 (TCF4) complex binding and transcriptional activity on ZEB1 promoter." (PMID 26098771, 2015). "In this study, through network pharmacology, it was demonstrated that AKT1, GSK3B, CASP3, TNF, and CCND1 may be the crucial targets of COP in bladder cancer treatment." (PMID 41287122, 2025). "AKT1, GSK3B, CASP3, TNF, CCND1 are the main targets of COP in the treatment of bladder cancer." (PMID 41287122, 2025). "This study investigated the effects of microRNA-135a (miR-135a) targeting of glycogen synthase kinase 3β (GSK3β) on the epithelial–mesenchymal transition (EMT), migration and invasion of bladder cancer (BC) cells by mediating the Wnt/β-catenin signaling pathway." (PMID 29350680, 2018). "CytoNCA plug-in analysis showed that the PI3K-Akt signaling pathway (degree = 9) may be the key pathway in the treatment of bladder cancer by COP, and AKT1 (degree = 12), GSK3B (degree = 10), CASP3 (degree = 10), TNF (degree = 8) and CCND1 (degree = 8) were considered to be the main hub targets." (PMID 41287122, 2025). "Another group showed that TRIM26 expression was increased in human bladder cancer tissues and cell lines, and knocking down TRIM26 significantly inhibited the proliferation, migration, and invasion of bladder cancer cells through the Akt/GSK3β/β-catenin pathway." (PMID 36249749, 2022). "In conclusion, we believe that these five target genes (GSK3B, CDC20, TPX2, AURKA and CCNE1) may promote the occurrence of bladder cancer and lead to poor prognosis.We explored the potential therapeutic targets of aspirin for bladder cancer by comprehensive bioinformatics analysis." (PMID 36316768, 2022). "Although GSK-3β is generally considered to negatively regulate cell growth, GSK-3β inhibitors have been found to reduce colon and ovarian tumor cell growth; these drugs may be appropriate in bladder cancer because of their effects on p21." (PMID 21864408, 2011).
leukemia (60 papers, 2009 to 2025). A malignant (clonal) hematologic disorder, involving hematopoietic stem cells and characterized by the presence of primitive or atypical myeloid or lymphoid cells in the bone marrow and the blood. "Inhibiting GSK3β kinase causes significant proliferation defects in various leukemia cell types, leading to apoptosis." (PMID 40805157, 2025). "For example, GSK3β has a key oncogenic role in leukemia with MLL mutations and intestinal neuroendocrine tumors." (PMID 33498808, 2021). "High levels of phosphorylated GSK3β are associated with poor prognosis in leukemia cells." (PMID 36739272, 2023). "Naïve ESCs are readily achieved by adding two chemical inhibitors (MEK1 inhibitor: iMEK1 and GSK3β inhibitor: iGSK3β) upon exposure of leukemia inhibitor factors (LIF; hereafter LIF/2i) with bME." (PMID 40010136, 2025). "For example, hsa_circ_0121582 was found to inhibit leukemia cell proliferation by recruiting DNA demethylase TET1 to the promoter region of GSK3β." (PMID 37124518, 2023). "BIO is a selective inhibitor of GSK3β that was initially demonstrated to suppress proliferation of human leukemia TF-1, HL-60, K562, and U937 cells." (PMID 36481875, 2022). "A study revealed that the in vivo administration of a GSK-3β inhibitor delayed tumor formation in a mouse model of leukemia." (PMID 35008789, 2021). "Loss of GSK-3α induces cell differentiation in AML, and a GSK-3β inhibitor suppresses cell growth and induces apoptosis in leukemia cells." (PMID 35008789, 2021). "Both bioinformatics prediction and luciferase assay indicated that AXIN2 and glycogen synthase kinase 3 beta (GSK-3β) were the direct targets of miR-1246 in leukemia cells." (PMID 34093820, 2021). "In vivo studies showed that leukemia progenitor cells harboring this misspliced GSK3β gene displayed enhanced β-catenin expression, which was required for the self-renewal of leukemia stem cells (LSCs)." (PMID 32101138, 2020). "It was also reported that GSK3β inhibitors suppress Bcl2-mediated and α5/β1-integrin-dependent cell survival pathways, thereby eliminating primitive leukemia progenitor/stem cells." (PMID 32503133, 2020). "In leukemia, GSK3β maintains the mixed-lineage leukemia (MLL) SC transcriptional program mediated by homeobox (HOX)." (PMID 32503133, 2020). "For instance, treatment of cells with BIO, a potent GSK-3β inhibitor, suppressed cell growth, induced apoptosis in leukemic cells and delayed tumor formation in a mouse model of leukemia." (PMID 27579985, 2016). "Some of the PPP3CA interactor proteins implicated in leukemia pathobiology such as BCL11b, NPM1, GSK3β and Rb were further validated in Jurkat T-ALL cells expressing constitutively active PPP3CA*." (PMID 27304189, 2016). "Maintenance of these ground state cells is possible using a combination of basic fibroblast growth factor and human leukemia inhibitory factor together with dual inhibition of glycogen synthase kinase 3 beta, and mitogen‐activated protein kinase kinase (MEK)." (PMID 26119873, 2015). "In this study, we show that cordycepin selectively suppresses cell proliferation via regulating GSK-3β/β-catenin signaling in leukemia cells." (PMID 24086728, 2013). "Whereas GSK3β phosphorylates and stabilizes p27Kip1 in normal cells, it down-regulates p27Kip1 in leukemia cells and selectively maintains the survival and proliferation of these cells." (PMID 23408967, 2013). "Here, we investigated the relationship between GSK-3β inhibition and NF-κB in apoptosis of pediatric primary leukemia cells obtained from 39 newly diagnosed ALL children in China." (PMID 21110852, 2010). "Recent studies show that GSK-3β has an important function in pathogenesis of human cancer, including leukaemia, pancreatic, prostate, colorectal, ovarian, thyroid and brain carcinomas." (PMID 19920820, 2009).